LEP (leptin)
Diseases named in the same sentence as LEP in open-access papers (continued):
Sharing a sentence is not in itself a finding about the gene and the disease.
cancer (continued). "Furthermore, leptin inhibits apoptosis of cancer cells by stimulating phosphorylation of IκBα, IκB kinase α (IKKα), IκB kinase β (IKKβ), and NIK in a dose-dependent manner." (PMID 36578551, 2022). "In addition to the regulation of body weight, LEP was also identified to be involved in insulin resistance, cancer cell inflammation, oxidative stress, cell proliferation, apoptosis, angiogenesis, and antitumor immune regulation." (PMID 35223490, 2022). "Cancer-associated adipocytes (CATs), another type of stromal cell in the TME, have been shown to promote carcinogenesis through obesity-associated hormones (e.g., leptin), vascular endothelial growth factor (VEGF), and cytokine effects on cancer-prone host cells." (PMID 36428777, 2022). "Experimental models have shown that adipokines such as leptin and hepatocyte growth factor may regulate cancer cell proliferation and invasiveness." (PMID 36249201, 2022). "For example, as previously discussed in this review, leptin may play a role in cancer cell proliferation and apoptosis." (PMID 36361914, 2022). "Furthermore, an anti-apoptotic role of leptin was also observed in ovarian carcinogenesis through the blockade of caspase expression, which further stimulates cancer cell proliferation." (PMID 35681689, 2022). "Our clinical data showed that leptin expression was positively associated with metastatic features in patients with NPC, indicating that leptin may participate in cancer motility." (PMID 35778755, 2022). "Among all adipokines, the role of leptin in cancer is the most studied." (PMID 36291097, 2022). "Furthermore, obesity and diabetes alters the production of endotrophin, leptin, adiponectin, angiopoietins, bone morphogenic proteins, and other adipokines, which can also affect cancer cell growth and survival." (PMID 35984550, 2022). "This tissue secretes adipocytokines such as visfatin, resistin, and leptin, which may be helpful in the prognosis and diagnosis of cancer, which can be beneficial for cancer prognosis and diagnosis." (PMID 36415563, 2022). "The expression of leptin positively correlated with cancer cell stemness." (PMID 35545767, 2022). "Although leptin is mainly expressed in adipose tissues, it has been detected in many other tissues/cells such as the brain, muscle, and stomach, as well as different types of cancer." (PMID 35778755, 2022). "Indeed, leptin‐induced angiogenesis is a common occurrence in tumours and leptin levels are elevated in several types of cancers from human patients." (PMID 36424766, 2022). "It has been demonstrated that leptin is an upstream regulator of VEGF expression in endothelial and cancer cells; accordingly, insufficient fasting-induced adipose-VEGF induction by leptin deficiency may undermine the WAT browning induced by IF in ob/ob mice." (PMID 35267959, 2022). "First, leptin has been shown to increase cellular migration in both cancer and wound healing contexts in mammals, and future studies could involve tracers to better track cellular movements." (PMID 36093099, 2022). "Additionally, leptin promotes expression of epithelial-to-mesenchymal transcription factors, cancer stem cell activity, expression of metastatic TGFβ1 pathway, in part by activation of inflammasomes." (PMID 35186923, 2022). "Leptin is a critical oncogenic factor released by adipocytes as an adipokine into the tumor microenvironment, where it promotes tumor development by activating cancer stem cell (CSC) molecular regulators Notch, Hedgehog, and Wnt/β-catenin signaling." (PMID 37529006, 2022). "The OR of the L/A ratio [6.0 (95% CI: 3.2–11.9)] was higher than those of leptin alone [3.2 (95% CI: 1.8–5.8)] or adiponectin alone [0.5 (95% CI: 0.3–0.9)], suggesting that L/A ratios in individuals may better indicate cancer growth and proliferation." (PMID 36578551, 2022).
cancer (continued). "Leptin can activate transcriptional programs for several cellular processes, such as cell growth, proliferation, survival, migration and differentiation, all of which is commonly dysregulated in cancer." (PMID 34951691, 2022). "Of note, our group previously reviewed the striking role of leptin in other conditions that involve female reproduction, pregnancy, gestational diabetes, non-alcoholic fatty liver disease, atopic dermatitis, and even cancer." (PMID 36555171, 2022). "In addition, leptin attenuates the outcome of cancer therapies and thus promotes tumor progression by inducing expression of factors such as ACTC1 and Notch." (PMID 35778755, 2022). "Furthermore, leptin induces proliferation, migration, and invasion and suppresses apoptosis of cancer cells." (PMID 36505829, 2022). "Multiple biologicalGO enrichments in the candidates could be dissected, for example,response to leptin and regulation of proteolysis increased in cancer(including STAT3 and transgelin (TAGL))." (PMID 35605973, 2022). "In addition to the biological function of the leptin axis in cancer, its clinical and prognostic significance in multiple cancer types is illustrated." (PMID 33799880, 2021). "In addition to the phenotype of increased cancer cell migration observed in this study, leptin has been reported to regulate metastasis in various types of cancer." (PMID 33804101, 2021). "Leptin mutants, leptin peptide antagonists, and neutralizing antibodies, have been shown to possess a promising therapeutic potential for the treatment of various diseases, including cancers." (PMID 34356668, 2021). "Leptin-mediated regulation toward JNK signaling is reported in several types of cancer." (PMID 33804101, 2021). "Cancer cells and the tumor microenvironment expressing leptin and leptin receptors suggest that the potential leptin autocrine/paracrine signaling loop could affect tumor progression." (PMID 33799880, 2021). "Leptin has also been shown to regulate cancer cell proliferation." (PMID 33799880, 2021). "For example, leptin has been reported to promote tumor growth through upregulation of c-Myc, which is a master regulator of mitochondrial glutaminolysis responsible for glutamine addiction in cancer cells." (PMID 33535537, 2021). "Noteworthy, the combined therapy with LCL-SIM and LCL-DMXAA strongly reduced (by 50–81%) the intratumor production of bFGF, IL-1 α/β, IL-6, TNFα, leptin and of eotaxin, which allow cancer cells to escape VEGF-targeted therapies, promoting tumor growth and metastasis." (PMID 34764332, 2021). "However, since both leptin and adiponectin exhibit multifaceted roles in cancer metabolism, a wiser therapeutic strategy is to exploit their downstream targets, which control essential metabolic pathways in tumors." (PMID 33535537, 2021). "While adiponectin possesses potent antitumor activities via various mechanisms, leptin has been found to be correlated with cancer aggressiveness and promote tumor growth, either directly via oncogenic signaling or indirectly through regulation of immune response and angiogenesis." (PMID 33226729, 2021). "However, augmented tumor formation is observed for several cancers, including cancers of the liver, kidney and pancreas in ob/ob and db/db compared with wildtype mice suggesting leptin-independent mechanisms." (PMID 33987528, 2021). "Moreover, leptin and adiponectin, which play a role in cancer biology, are both influenced by VAT and the subcutaneous adipose tissue." (PMID 33823929, 2021). "For those reasons, the purpose of this article is to review the available literature concerning the relationship between leptin and chronic inflammation in cancer and the role of leptin as both a bad and good actor in the disease to better understand the possible dual effect of this hormone." (PMID 34202969, 2021).
cancer (continued). "In general, the expression of leptin and its receptor were found to be associated with poor prognosis in the majority of cancers studied; however, negative correlation with cancer progression has also been reported." (PMID 34210055, 2021). "In contrast, other investigations revealed that leptin suppresses OXPHOS in cancer cells." (PMID 33535537, 2021). "In addition, leptin plays a critical role in regulating appetite and energy balance, and it has been shown to activate cell proliferation and survival in cancer cells, including those of the prostate, breast, endometrium, and colon." (PMID 33708630, 2021). "The leptin to adiponectin ratio in serum is an important indicator of cancer risk." (PMID 34131208, 2021). "Notably, blockage of SREBPs abolishes leptin-stimulated cancer cell proliferation, migration, and invasion, indicating the critical role of SREBPs-dependent lipogenesis in oncogenic actions of leptin." (PMID 33535537, 2021). "Furthermore, the prognostic significance of leptin in various types of cancer and the ability to noninvasively detect leptin levels in serum samples have attracted attention for potential clinical applications." (PMID 33799880, 2021). "Hence, the incubation of leptin with OC cells ameliorates the influence of paclitaxel/Taxol on cancer cell microtubules." (PMID 33809784, 2021). "Although leptin possesses the physiological functions as an inhibitor of lipogenesis, emerging evidence suggests a promoting role of leptin in de novo biosynthesis of fatty acids in cancer-related contexts." (PMID 33535537, 2021). "Adiponectin can downregulate the expression of ER-α through the HO-1 signaling pathway, thereby blocking the activation of ER-α induced by leptin, blocking the formation of leptin inflammasomes, inhibiting the effect of leptin in promoting tumor growth, and suppressing cancer." (PMID 34485124, 2021). "Emerging findings have demonstrated the direct and indirect biological effects of leptin in regulating cancer proliferation, metastasis, angiogenesis and chemoresistance, warranting the exploration of the underlying molecular mechanisms to develop a novel therapeutic strategy." (PMID 33799880, 2021). "Moreover, leptin treatment of cancer cells modulates processes such as metabolic reprogramming and reactive oxygen species production." (PMID 33987528, 2021). "A study aiming to counteract leptin-mediated cancer metastasis was reported." (PMID 33799880, 2021). "Instead, more specific metabolic targets may be aimed to counteract leptin-promoted cancer metabolism." (PMID 33535537, 2021). "In addition, we have demonstrated for the first time that SREBP‐1 induction, mediated via autophagy, plays a critical role in leptin‐induced metabolic alterations in cancer cells." (PMID 33226729, 2021). "These survival results support an “antitumoral-like” role of leptin that could be attributed to a more effective response to cancer therapies in obese patients, named also the “leptin paradox” in cancer as reviewed recently by Sánchez-Margalet’s group." (PMID 34884678, 2021). "Recent data regarding the immunotherapy of cancer have revealed that overweight leads to a more effective response and leptin may probably be involved in this beneficial process." (PMID 34202969, 2021). "Several studies reported that Acrp30 and leptin might influence the motility and migration of cancer cells." (PMID 33587254, 2021). "Leptin has a key role in energy metabolism but it is also an important regulator of different physiological and pathological processes, including activation of the immune system and cancer progression." (PMID 34356668, 2021). "Leptin and Ob-R expression has been found to play carcinogenic roles, since its binding activates the Akt signaling pathway in esophageal cancer cells via multiple atorvastatin sensitive small GTPases, leading to the growth and antiapoptosis of cancer cells." (PMID 34202969, 2021).
cancer (continued). "Increasing clinical studies indicate the correlation of leptin with cancer metastasis." (PMID 33804101, 2021). "Given the fact that leptin and adiponectin regulate autophagy and mTOR activation, these adipokines may play a multifaceted role in cancer cell-specific glutamine metabolism." (PMID 33535537, 2021). "Leptin signaling is also known to have angiogenic effects in multiple cancers including HCC." (PMID 34348664, 2021). "Given the critical role of autophagy and leptin/adiponectin in the regulation of cancer metabolism, it could be assumed that autophagy mediates cancer-related metabolic alterations induced by these adipokines." (PMID 33535537, 2021). "Leptin induces muscle wasting in a zebrafish model of cancer cachexia." (PMID 34440723, 2021). "Although leptin has been well known to support tumor growth through multiple mechanisms, little effort has been made to examine the various metabolic effects in cancer cells and its potential roles in the pro‐carcinogenic effects of this adipokine." (PMID 33226729, 2021). "Recently, obese patients have been shown to obtain better responses to cancer immunotherapies, that may be related to leptin levels." (PMID 34202969, 2021). "Additionally, it is suggested that the elevated serum leptin concentration in patients with stage I to III NSCLC plays an important role in the progression of this type of cancer." (PMID 33334030, 2020). "Like leptin, it may act as an autocrine and/or paracrine hormone and contribute to cancer cell colonization." (PMID 33213024, 2020). "Reports indicated that the presence of high serum leptin leads to the progression of cancer." (PMID 32802842, 2020). "The identification of altered levels of leptin and leptin receptor proteins in tumour tissues may lead to targeted treatment for cancer." (PMID 32802842, 2020). "Furthermore, the inhibitory effect of the miR-34a mimic on PAI-1 was reversed in different cancer cells following leptin treatment." (PMID 33371368, 2020). "Together, the available evidence indicates that the abundance of energy-rich metabolites (such as glucose, fatty acids or amino acids) and/or trophic factors (such as insulin, insulin-like growth factor and leptin) can affect tumor immuno-surveillance and stimulate the proliferation of cancer cells." (PMID 32375310, 2020). "Additionally, leptin signaling induced significant changes in the expression of genes involved in cancer progression and chemoresistance in TNBC cells." (PMID 32471192, 2020). "The majority of the published data deal with the potential correlations between circulating leptin, adiponectin, and resistin levels with systemic inflammation and cachexia in obesity-related cancers, while data regarding resistin, visfatin, apelin are more limited." (PMID 32660156, 2020). "In addition, miR-34a mimic-induced elevation of miR-34a in cancer cells was significantly abrogated after treatment with leptin." (PMID 33371368, 2020). "Additionally, low leptin predicts poor survival in cancer cachexia, while induction of autophagy in response to CR contributes to muscle wasting in mouse models of cachexia." (PMID 33224954, 2020). "LEP was reported to promote cancer cell migration and invasion." (PMID 33194689, 2020). "The correlation between leptin levels and cancer differs according to cancer types." (PMID 32660156, 2020). "In addition to adipose tissue, cancer cells can also secrete leptin and overexpress leptin receptors." (PMID 32033341, 2020). "In recent years it has been reported that leptin also plays a significant role within the tumor microenvironment, especially when its expression is chronically elevated, contributing to the development and progression of different types of cancer." (PMID 33334030, 2020). "Moreover, it has been demonstrated that leptin can be a co-factor for TGF-β in cancer using an in vitro model of kidney fibroblasts whereby leptin treatment enhances SMAD2/3 phosphorylation by TGF-β32,33." (PMID 32968152, 2020).
cancer (continued). "Morphologically, leptin was primarily localized in the cytoplasm of the cancer cells." (PMID 32596369, 2020). "Hyperactive leptin signaling potentiates these molecular mediators and leads to the activation of various oncogenic pathways resulting in enhanced proliferation and invasion of cancer cells." (PMID 33511131, 2020). "The availability of PLOD2 is one way by which IL-6 and leptin may influence collagen re-organization to create a “highway” for cancer cell migration and invasion to promote metastasis." (PMID 32033341, 2020). "Leptin and adiponectin in cancer biology work in an inverse manner, since leptin plays a crucial role in the promotion of tumour angiogenesis, cell invasion, and metastasis, whereas adiponectin possesses anti-tumour properties, including anti-proliferative, anti-migratory, and pro-apoptotic actions." (PMID 32512860, 2020). "Leptin inhibits cell death and stimulates endothelial cell growth in a Bcl-2-dependent strategy, contributing to the proangiogenic activity that can be recapitulated in cancer." (PMID 32354024, 2020). "Leptin signalling in CSC is also involved in cancer recurrence and drug resistance." (PMID 32033341, 2020). "In addition, depletion of OBR inhibited the leptin-induced accumulation of p-STAT3 in the nucleus of cancer cells." (PMID 33371368, 2020). "High levels of leptin may play an important role in promoting cancer cell migration, proliferation, survival, and angiogenesis." (PMID 33256658, 2020). "To address this issue, we delivered Bo1 cancer cells to leptin–/– (ob/ob) or adiponectin–/– mice." (PMID 32879136, 2020). "Thus, features such as EPB41, PSMA1, FGFR3, MRAS, and LEP which were involved in cancer-related pathways and with high PPI degrees (>/ = 10) were considered as PRBs for further analysis." (PMID 32528533, 2020). "They found positive ObR expression in 67 carcinoma samples, of which 45 showed strong leptin expression and 22 weak leptin expression; both ObR-b and leptin expression were correlated with the depth of tumor invasion, venous and lymphatic metastasis, and TMN stage." (PMID 33334030, 2020). "However, overexpression of leptin and activation of ObR has been reported in various cancers, such as those of the stomach and mammary gland, and is mediated by inflammation, angiogenesis, stemness, and epithelial–mesenchymal transition (EMT) and progression." (PMID 31141984, 2019). "This hypothesis is supported by several recent pieces of evidence, as the increase of leptin concentration in the microenvironment was related to the occurrence and metastasis of several types of cancer." (PMID 31119158, 2019). "The involvement of leptin and its receptor has been widely reported in many cancer types such as breast, colorectal prostate, gastric mucosa (Lee., 2014), esophagal, ovarian (Kato et., 2015), and endometrial cancers." (PMID 30803210, 2019). "Thus, a cardinal role of leptin in autophagy and suppression of apoptosis in cancer cells has been proposed as well." (PMID 31380268, 2019). "Leptin is an additional metabolic hormone with direct effects on cancer and sleep." (PMID 31174326, 2019). "In addition, an overexpression of leptin and its receptor (OB-R) has been reported in many cancer types, including thyroid malignancies." (PMID 30906321, 2019). "Further investigation is needed to explore a threshold of leptin which could stimulate the development of cancer." (PMID 30702563, 2019). "In addition, associated with obesity reduced secretion of adiponectin and increased secretion of leptin by adipose tissue can promote cancer development in obese." (PMID 30845725, 2019). "Indeed, many studies have demonstrated leptin's influence on the expression of cell cycle modulators, cancer cell proliferation and transformation, and cell migration and invasion." (PMID 30906321, 2019).